SEC62 (SEC62 preprotein translocation factor)
Diseases named in the same sentence as SEC62 in open-access papers (continued):
Sharing a sentence is not in itself a finding about the gene and the disease.
SEC62 also shares sentences with these, for which no sentence is quoted: fibrosarcoma (2 papers); glioblastoma (2); lung adenocarcinoma (2); schizophrenia (2); channelopathies (1); endometrial cancer (1); esophageal cancer (1); invasive carcinoma (1); liver cancer (1); liver cirrhosis (1); retinal degeneration (1); Spitz nevi (1); triple-negative breast carcinoma (1); uterine endometrioid carcinoma (1).